ADAM17 (ADAM metallopeptidase domain 17)
Diseases named in the same sentence as ADAM17 in open-access papers (continued):
Sharing a sentence is not in itself a finding about the gene and the disease.
cancer (continued). "The search for ADAM17 came up with 175 results of single nucleotide variations (SNVs) within unique cancer tissue samples." (PMID 33143292, 2020). "Despite the success of targeting ADAM17 using small-molecule inhibitors (SMIs) and siRNA in cancer models, the clinical benefits of such approaches are questionable." (PMID 31438559, 2019). "On this note, ADAM17 is associated with shedding of several EGFR family ligands (e.g., EGF, TGFα, and amphiregulin) in NSCLC and other cancers." (PMID 30833304, 2019). "This led us to the conclusion that this mutation, which has been found in cancer tissue from two separate individuals within the caecum and the brain (COSMIC database, Sanger Institute), severely impairs pro-domain and thus ADAM17 function." (PMID 31060243, 2019). "Small molecule inhibitors (SMIs) of ADAM17 also suppress the growth of various human cancer cell line xenografts." (PMID 30833304, 2019). "Given that ADAM17 sheds over 70 substrates, there lies the need to investigate the potential role of other ADAM17 substrates in cancer." (PMID 31438559, 2019). "The role of the protease ADAM17 in cancer development will be discussed in detail in later sections of this review." (PMID 31438559, 2019). "In this regard, a key finding of our study was the robust anti‐cancer activity of a novel class of highly selective ADAM17 inhibitor, A17pro, modeled on its auto‐inhibitory prodomain." (PMID 30833304, 2019). "The role of ADAM17 in cancer has been widely reported, especially following the discovery of a direct effect of ADAM17 on the release of TNFα." (PMID 31565100, 2019). "Our study identifies ADAM17 as a key cooperating factor and druggable target in oncogenic KRAS‐driven LAC and thus provides the rationale to employ ADAM17‐based therapeutic strategies for targeting oncogenic KRAS‐addicted cancers." (PMID 30833304, 2019). "Although ADAM17 has been shown to be involved in various important cell functions as well as in cancer metabolism, its maturation and regulation of proteolytic function have only been poorly understood." (PMID 31060243, 2019). "The role of ADAM17 and IL-6 trans-signaling in inflammation and cancer will therefore be reviewed in the following paragraphs." (PMID 31694340, 2019). "The Adamx/ex mice have been used extensively to identify the role of ADAM17 in inflammation and cancer." (PMID 31438559, 2019). "In other cancer cells, many genes have been identified as miR-338-3p targets, including ADAM17, PREX2a, ZEB2, Sox4, SMO, MACC1, and IRS2." (PMID 29618948, 2018). "Among the genes with the mutations identified, they include Cancer Gene Census genes and other cancer-associated genes with three of which carried multiple mutations (ARID1B, CSMD1 and ADAM17)." (PMID 30627328, 2018). "In this work we show that BPA and NP differentially induce apoptosis in cancer cell lines in a mechanism dependent upon ADAM17 and extracellular Ca2+, and we provide insights of possible mechanisms involved in the activation of ADAM17 by BPA and NP." (PMID 30065191, 2018). "In particular, ADAM10 and ADAM17 appear to promote cancer progression by releasing HER/EGFR ligands." (PMID 30081852, 2018). "As a whole, these results strongly suggest that in vitro BPA and NP induce ADAM17-dependent apoptosis in at least two different cancer cell lines, LNCaP and A2780." (PMID 30065191, 2018). "ADAM17 is a molecular switch that controls immune responses, tissue regeneration, and cancer development." (PMID 30092799, 2018). "ADAM-10 and ADAM-17 facilitate the shedding of multiple ErbB ligands, which are overexpressed in several cancers and promote tumorigenesis upon binding to ErbB receptors." (PMID 29393911, 2018). "Hopefully, future clinical trials will be able to dissect what type of cancer patients will benefit from using emerging ADAM17 therapeutic agents." (PMID 29230082, 2017).
cancer (continued). "ADAM17 has potential roles in regulating various cell surface proteins on the cancer cell surface as well as growth factors and cytokines in the tumor microenvironment." (PMID 29029414, 2017). "The benefit from the use of an ADAM17 inhibitor to aid other therapeutic agents in cancer immunosurveillance is unclear at this time." (PMID 29230082, 2017). "The proper clinical trial for cancer will likely depend on multiple factors including the cancer type, the cancer's genome, and the drugs that are chosen to be used in addition to an ADAM17 inhibitor." (PMID 29230082, 2017). "Studies suggest that c-MET activation is a potential mechanism of resistance not only to MEK1/2 inhibitors but also to ADAM17 inhibitors in certain types of cancer." (PMID 29230082, 2017). "With over 80 known substrates now reported to be processed by ADAM17, clearly, the enzyme plays a major role in the areas of cancer and inflammation." (PMID 29230082, 2017). "As there are many reviews on substrates and cancer, this one will focus on more recent substrates for ADAM17 which are yet to be discussed." (PMID 29230082, 2017). "Nevertheless, targeting ADAM17 with a selective inhibitor still seems a viable and attractive approach for use in the clinic for cancer indications." (PMID 29230082, 2017). "This review focuses on substrates and inhibitors identified more recently for ADAM17 and their role in cancer and inflammation." (PMID 29230082, 2017). "The ADAMs family sheddases, ADAM10 and ADAM17, have been implicated in the proteolytic cleavage of NKG2DL in several types of cancer cells." (PMID 28404876, 2017). "ADAM17 is an activator of the Notch pathway and is overexpressed in a variety of diseases, including cancers." (PMID 26993601, 2016). "As ADAM17 is often overexpressed in tumors and promotes their progression, it has been recognized as a promising target for cancer therapy." (PMID 26176220, 2015). "The antilymphangiogenic effects of ADAM17 silencing in lymphatic endothelial cells suggest further relevance of ADAM17 as a potential target in cancer therapy." (PMID 26176220, 2015). "The ADAM-17/TACE have been found to be key players for the regulation of cell migration and invasion in cancer." (PMID 25825984, 2015). "Increased expression of ADAM17 is not a trigger of pathologies, but rather allows for the full manifestation of the activity of ADAM17 substrates whose expression is stimulated during immune activation or cancer-related processes." (PMID 26176220, 2015). "According to current views, the major mechanism by which ADAM17 supports cancer development involves shedding, and thus activation, of growth factors of the EGF family such as TGFα, HB-EGF, amphiregulin or neuregulins." (PMID 26176220, 2015). "The metalloproteases MMP-2, MMP-9, CD13 and ADAM17 are already considered to be useful markers in several cancers." (PMID 25246708, 2014). "To further validate these data, we used A431 carcinoma cell line knockdown for ADAM17 gene to analyze Erk phosphorylation state and it confirmed lower phosphorylation levels in Erk (n = 2, Fisher’s exact test, p = 0.0001)." (PMID 24495306, 2014). "To further validate these data in another cell line, we have used A431 carcinoma cell line silenced for ADAM17 expression in adhesion assay." (PMID 24495306, 2014). "It has been reported that ADAM17 contributes to cancer cell progression through activation of the EGFR/PI3K/Akt and EGFR/Ras/MAPK/Erk signaling pathways." (PMID 24843386, 2013). "There is no such study yet in cortex development, but some information about regulation of ADAM17 expression are available in cancer and inflammation fields." (PMID 23755270, 2013). "VASN, vasorin, is a transforming growth factor beta (TGF-β) trap, its biology is regulated by ADAM17, and it appears to play a role in epithelial to mesenchymal transition in other cancer types." (PMID 23251904, 2012).
cancer (continued). "Throughout the last decade ADAM17 has been recognized as a new, promising target for cancer therapy." (PMID 23251384, 2012). "ADAM 17 (TNF-α converting enzyme, TACE) is a potential target for cancer therapy, but the small molecule inhibitors reported to date are not specific to this ADAM family member." (PMID 22792380, 2012). "ADAM17 is also a sheddase for EpCAM, homophilic cell adhesion molecule, often highly expressed on carcinoma cells." (PMID 23251384, 2012). "ADAM17 is post-translationally regulated by the inactive rhomboid pseudoproteases iRhom1 and iRhom2, and dysregulation of this signaling axis contributes to diseases ranging from chronic inflammation to cancer." (PMID 42024498, 2026). "These functions highlight ADAM17’s central role in both physiological and pathological processes, making it a significant target for therapeutic interventions in diseases characterized by chronic inflammation and cancer." (PMID 41050403, 2025). "ADAM17 is a crucial transmembrane protease involved in various physiological and pathological processes, including inflammatory responses, cell proliferation, and cancer progression." (PMID 41050403, 2025). "Therefore, “CD16a shedding” is a target to promote ADCC by NK cells in cancer immunotherapy research but it is limited by the ADAM17’s multi-substrate specificity." (PMID 41219228, 2025). "To delve into the relationship between ADAM17 and gastric mucosal inflammation-related cancer, we analyzed public databases, including TPM-formatted RNA-seq data from the TCGA and GTEx datasets, to investigate the transcriptional variations between GC and normal tissues." (PMID 40143211, 2025). "However, despite its documented role in cancer progression, therapeutics targeting ADAM17 have been hindered by severe side effects due to its ubiquitous expression, wide variety of substrates, and catalytic domain conserved amongst other metalloproteinases." (PMID 40727266, 2024). "Altogether, these findings suggest that ADAM17 stimulates cancer progression." (PMID 38317965, 2024). "The protease ADAM17 plays an important role in inflammation and cancer and is regulated by iRhom2." (PMID 38409522, 2024). "Nevertheless, the insights gained from our structures of the ADAM17/iRhom2 complex, including its regulatory mechanisms, provide a mechanistic basis for the development of future therapeutics to target ADAM17-dependent shedding in inflammatory diseases and cancer." (PMID 38781971, 2024). "ADAM17 has been shown to drive therapeutic resistance in cancer, raising the possibility that ADAM17 may be complicit in EREG-mediated drug resistance." (PMID 38398101, 2024). "Several ADAM17 inhibitors have been screened for cancer research, but the high homology between metalloproteinases active sites has limited the development of highly specific ADAM17 small molecule inhibitors, and the clinical use has been limited due to its potential side effects." (PMID 38799171, 2024). "On the one hand, our group has reported that the trans interaction between ADAM17 on TEVs and integrin α5β1 on target cells is involved in the binding and uptake of cancer-derived EVs, supporting a role for ADAM17 on TEVs as an integrin ligand and adhesion molecule." (PMID 38542421, 2024). "Thus, ADAM17 plays a crucial role in various physiological and pathological processes, such as cell growth, regeneration, differentiation, inflammation, and cancer progression." (PMID 37175410, 2023). "Hence, blocking ADAM17 by targeting iRhoms is also a promising treatment strategy against cancer progression." (PMID 37119365, 2023). "This further confirms the important role of ADAM17 in cancer development and immune evasion." (PMID 38069391, 2023). "Inhibition of ADAM17 has been proposed as possible cancer treatment." (PMID 36733457, 2023). "Our findings indicate that ADAM17 could be considered a promising target for NK cell HIV-1 immunotherapies similar to cancer immunotherapies." (PMID 37669308, 2023).
cancer (continued). "ADAM17 was previously identified to play a role in IR-induced cancer cell migration." (PMID 36998455, 2023). "This implies that cancer cells overexpressing ADAM17 can exhibit elevated levels of secreted proteins, which may enhance their resistance to adverse external environments." (PMID 37175410, 2023). "Cancer cells can also suppress the NK-mediated ADCC by downregulating levels of CD16 on the surface of NK cells through the enhancement of the proteolytic activity of the enzyme ADAM17." (PMID 38077389, 2023). "In addition, the significance of ADAM17 in cancer development is based on its direct effect on the release of TNFα." (PMID 35565436, 2022). "In cancer, the pro-angiogenic role of ADAM17 is related to the shedding and activation of different pro-angiogenic factors such as HB-EGF, neuregulin-1 or TGF-alpha or, conversely, to the downregulation of the natural inhibitor of angiogenesis thrombospondin-1 (TSP1)." (PMID 36140519, 2022). "So far, however, treating cancer with ADAM17 inhibitors failed in clinical trials, mainly due to specificity problems of the inhibitory molecules and lack of knowledge about the function of ADAM17 and other related metalloproteinases in cancer and the TME." (PMID 35998057, 2022). "Moreover, the interaction between the integrin α5β1 on CRC cells and its ligand ADAM17 on exosomes mediates the uptake of exosomes by cancer recipient cells, which can bear relevance during the peritoneal dissemination of CRC." (PMID 35158891, 2022). "Yet, we show that the secretion of both HB-EGF and AREG is crucial for the invasion-supporting phenotype of the macrophages, and we were able to rescue the impaired ability of macrophages educated by Adam17–/– cells to induce cancer cell invasion by adding rHB-EGF or rAREG to the cocultures." (PMID 35998057, 2022). "Together, these data further strengthen the role of ADAM17 as a potential cancer biomarker." (PMID 36293469, 2022). "This makes ADAM17 or ADAM10 an ideal intervention target for the treatment of malignant tumors." (PMID 36606198, 2022). "As ADAM17 plays an important and functional role in both cancer and fibrosis, it might be a potential drug target for treatment in these diseases, although the specificity is expected to be low, as ADAM17 is known to have a high number of substrates." (PMID 35625561, 2022). "Indeed, macrophages cocultured with ADAM17-reexpressing cells regained the ability to induce cancer cell invasion." (PMID 35998057, 2022). "High expression of ADAM17 significantly reduces the prognosis of patients with malignant tumors." (PMID 35720350, 2022). "We identified ADAM17, a sheddase upregulated in many cancer types, as a protein of interest." (PMID 35998057, 2022). "More IHC data are available from studies of ADAM17 expression in other cancer types." (PMID 36140519, 2022). "We then asked whether the addition of rHB-EGF or rAREG to Adam17–/– cancer cell-macrophage cocultures could rescue the invasion-supporting macrophage phenotype." (PMID 35998057, 2022). "Altogether these findings suggest that ADAM17 may support VEGF-alternative pathways for neo-angiogenesis in cancer." (PMID 36140519, 2022). "Our previous study showed that the expression of ADAM17 was associated with infiltration of multiple immune cells, including macrophages, in TCGA pan-cancer samples and yet the specific regulatory mechanism of ADAM17 is unknown." (PMID 36466812, 2022). "First, we evaluated whether we could confirm the role of cancer cell–derived ADAM17 expression on macrophage-induced cancer cell invasion in this model." (PMID 35998057, 2022). "In this regard, ADAM17 inhibition might alleviate the severe infections that occur in patients with malignant tumors." (PMID 36558177, 2022). "ADAM17 is a member of ADAMs family, which mediates the shedding and maturity of various membrane proteins such as HB-EGF, TNFα, NOTCH, and cadherins and is implicated in cancer progression." (PMID 35138218, 2022).
cancer (continued). "So, we asked whether macrophages polarized by cancer cells promote cancer cell invasion and whether that relies on ADAM17-mediated shedding of 1 or more factors from the cancer cells." (PMID 35998057, 2022). "Moreover, ADAM17–/– educated macrophages demonstrated a reduced ability to induce cancer cell invasion." (PMID 35998057, 2022). "Fittingly, ADAM17 activation is involved in the development of lung and colorectal cancer." (PMID 34228897, 2022). "Moreover, we and others have demonstrated a strong cancer-promoting function of ADAM17 activity in murine cancer models." (PMID 35998057, 2022). "Bioinformatics analysis aimed to explore the importance of the ADMA17 immune response in identifying different types of cancer that might benefit from anti-ADAM17 therapy." (PMID 35720350, 2022). "Given its ability to shed pro-inflammatory molecules, pro-tumorigenic substrates, adhesion molecules and other molecules involved in cancer progression, ADAM17 plays a multifunctional role in cancer progression that can vary among different tumors and stages of the disease." (PMID 33579029, 2021). "It is not very clear whether there are differences in glycosylation of ADAM17 between normal and cancer cells and so does the relationship of glycosylation and enzymatic activity." (PMID 34182543, 2021). "In this context, ADAM17 inhibition sensitized cancer cells to cisplatin-induced apoptosis." (PMID 33672843, 2021). "In addition to its extensively investigated role in cancer progression through modulation of the EGFR signaling pathway, ADAM17 regulates other features that are associated with the disease, which have been more recently characterized." (PMID 33579029, 2021). "Some anti-cancer therapies might inhibit the activity of ADAM17, which in theory would decrease the release of soluble ACE2 in the circulation or extracellular compartment and subsequently enhance the internalization of SARS-CoV-2 into the cells." (PMID 33809851, 2021). "Interestingly, blockers of ADAM17 have been considered for clinical trials in several diseases including cancer and type 1 and type 2 diabetes (NCT04630769, NCT02141451, NCT00312780, NCT04557228, NCT01223196)." (PMID 34884897, 2021). "ADAM17 blockade in combination with IL-15 may provide a new approach to improve NK cell persistence and function in cancer patients." (PMID 34367174, 2021). "Importantly, the key finding that ADAM17 inhibition sensitizes OvCa cells to cisplatin treatment was validated using our 3D culture system in established cell lines and in primary cancer cells, emphasizing the translational aspect of our work." (PMID 33922533, 2021). "However, miRNAs function as upstream regulators in ADAM17 cell signaling pathway and more and more studies focus on the regulation network of cancer-related miRNAs and ADAM family." (PMID 34182543, 2021). "Taken together, these results indicate a multifunctional role for ADAM17 in cancer." (PMID 33579029, 2021). "Finally, the implication of ADAM17 in different types of cancer is beginning to unravel and strategies to therapeutically target this metalloproteinase are being developed." (PMID 34576100, 2021). "In addition, the disintegrin domain of ADAM17 enabled cancer cells to interact with fibroblast and microenvironment, while soluble disintegrin impair this interaction and increased the proteolysis activity of ADAM17." (PMID 34182543, 2021). "ADAM17 is known to promote cancer cell migration under hypoxia, and whether or how ADAM17 plays a role in hypoxia-induced keratinocyte migration has not been identified." (PMID 34746310, 2021). "Furthermore, high levels of soluble EGFR ligands and elevated expression of ADAM17 correlate with poor cancer prognosis." (PMID 33579029, 2021). "Therefore, the ADAMs, particularly ADAM-10 and ADAM-17, have been described as the most prominent sheddases, being widely expressed and commonly over-expressed in cancer cells and involved in cleaving diverse substrates." (PMID 32948029, 2020).